LRRC45 (leucine rich repeat containing 45)
Description:
Component of the proteinaceous fiber-like linker between two centrioles, required for centrosome cohesion. Is probably involved in the early stages of ciliogenesis. Plays a role in the organization of centriolar satellites, likely by regulating the accumulation of centriolar satellite proteins, such as PCM1 and SSX2IP, at the centrosome.
Synonyms: MGC20806
Tractability: Antibody: its Gene Ontology location is reachable by antibodies, with high confidence. PROTAC: ubiquitination databases record sites on it.
Gene: Protein-coding gene on chromosome 17 (82,023,294 to 82,031,153, forward strand). Ensembl gene ENSG00000169683.
Subcellular location: Cytoplasm, cytoskeleton, microtubule organizing center, centrosome; Cytoplasm, cytoskeleton, cilium basal body; Cytoplasm, cytoskeleton, microtubule organizing center, centrosome, centriole
Subcellular location (Human Protein Atlas): Basal body; Centrosome; Cytosol; Mid piece; Plasma membrane; Principal piece
Gene Ontology:
Molecular function: protein binding
Biological process: cilium assembly; protein localization to centriolar satellite
Cellular component: centriole; centrosome; ciliary basal body
Genetic constraint (gnomAD): Loss-of-function variants: 77 observed, 72 expected, observed/expected ratio (o/e) 1.07, 90% interval 0.89 to 1.29. The synonymous counts are far from expectation, so gnomAD's model fits this gene poorly and the ratio says little. Missense variants: 937 observed, 742.81 expected, observed/expected ratio (o/e) 1.26, 90% interval 1.2 to 1.33. Synonymous variants: 429 observed, 312.45 expected, observed/expected ratio (o/e) 1.37, 90% interval 1.27 to 1.49.
Homologues: Orthologues: chimpanzee LRRC45 (99% identical), macaque LRRC45 (97% identical), rat Lrrc45 (84% identical), mouse Lrrc45 (84% identical), dog LRRC45 (83% identical), pig LRRC45 (82% identical), guinea pig LRRC45 (80% identical), zebrafish lrrc45 (59% identical), tropical clawed frog lrrc45 (53% identical). Paralogues in human: CEP83 (17% identical).
Diseases named in the same sentence as LRRC45 in open-access papers:
LRRC45 is named in the same sentence as 5 diseases in open-access papers, as found by Europe PMC text mining. Sharing a sentence is not in itself a finding about the gene and the disease. The quoted sentences say what the papers report.
lung carcinoma (2 papers, 2021 to 2025). "The study reported LRRC45 facilitate lung cancer progression through the upregulation of c-MYC and several other proteins." (PMID 41458604, 2025).
ciliopathy (1 paper, 2022). A genetic disorder of the cellular cilia or the cilia anchoring structures, the basal bodies, or of ciliary function. "Two unrelated participants have biallelic likely pathogenic variants in LRRC45, a putative novel ciliopathy disease gene." (PMID 34716235, 2022).
cone-rod dystrophy (1 paper, 2022). Inherited retinal dystrophies that belong to the group of pigmentary retinopathies. "However, we identified a second proband with LRRC45 variants within the cone-rod dystrophy recruitment category and with an ‘unsolved’ GMC exit questionnaire." (PMID 34716235, 2022).
LRRC45 also shares sentences with these, for which no sentence is quoted: chronic obstructive pulmonary disease (1 paper); pulmonary fibrosis (1).